TRAF2 (TNF receptor associated factor 2)
Diseases named in the same sentence as TRAF2 in open-access papers (continued):
Sharing a sentence is not in itself a finding about the gene and the disease.
tumor (continued). "In this review, we summarize the various TRAF2-related signaling pathways and their relevance for the oncogenic and tumor suppressive activities of TRAF2." (PMID 36011046, 2022). "A consequence of increased TRAF2 expression, as often observed in tumor cells, is that competition for TRAF2 loses functional relevance." (PMID 36011046, 2022). "The enrichment of TRAF2 in the tumor surrounding region suggests the progression of tumor cells in invading and penetrating the surrounding tissues, potentially aiding in the prognosis of the cancer stage." (PMID 36418351, 2022). "These regions contained tumor-related genes, such as Muc16, Pik3, and Bcl2 in amplification regions and Hras, Notch1, Apc2, Ccnd1, Batf2, Dapk3, Smarca4, Traf2, Traf3, Cdk3, and Cdh4 in deletion regions." (PMID 36424557, 2022). "In a context-dependent manner, TRAF2 promotes tumor development but it can also act as a tumor suppressor." (PMID 36011046, 2022). "In view of its often protumoral activities and its ICB antagonizing effects, TRAF2 is an obvious potential target for tumor therapy." (PMID 36011046, 2022). "In preclinical models, birinapant synergizes with TRAF2 inactivation to induce tumor volume reduction and extend survival in mice, likely impacting T cell functionality." (PMID 35296667, 2022). "Mechanistically, TRAF2 loss was shown to enhance CPI efficacy by lowering the tumor necrosis factor (TNF) cytotoxicity threshold and increasing T cell-mediated tumor cell apoptosis." (PMID 33508232, 2021). "Lys63-type ubiquitination by the E3 ligase TRAF2 is required for 4-1BB receptor internalization, its subsequent signaling from endosomes, and ultimately, for 4-1BB-dependent tumor rejection." (PMID 34639141, 2021). "TWEAK, which is widely expressed in monocytes/macrophages and is associated with inflammation, can promote lysosomal degradation of cIAP1/TRAF2 in tumor cells." (PMID 34711816, 2021). "Two major signals from our study, STAT3 and TRAF2, are involved in miR-671-5p-regulated tumor migration." (PMID 35052701, 2021). "As a hub scaffold protein in signal transduction, especially the role in the regulation of NF-κB activity, abnormal expression of TRAF2 is often related to tumor resistance." (PMID 32566659, 2020). "As an essential adaptor protein involved in cell signaling transduction, a large number of literature has revealed that TRAF2 was involved in tumor development and progression." (PMID 32566659, 2020). "TNF-α, TRAIL and the FasL-mediated/TRAF2/NF-κB survival pathway can protect tumor cells from cell death." (PMID 31462894, 2019). "Second, a TRAF2-mediated NF-κB transcriptional survival program protects tumor cells against cell death." (PMID 29515108, 2018). "TRAF2 overexpression also enhanced the level of tumour-derived TNFα, a known an inhibitory factor of osteoblast survival and differentiation." (PMID 29311633, 2018). "In vivo, TRAF2 overexpression in the parental MDA-231-P cells enhanced tumour growth after orthotopic injection into the mammary fat pad of mice but failed to promote the metastasis of these cells to bone." (PMID 29311633, 2018). "Taken together, it is perplexing that both tumor suppressive and oncogenic roles of TRAF2 have been reported in the same type of human cancers." (PMID 30294322, 2018). "Overexpression of TRAF2 in these cells markedly increased tumour growth in bone and enhanced their ability to cause osteolysis." (PMID 29311633, 2018). "TRAF2 has diverse functions in inflammation, and its upregulation in mammary epithelial cells enhances their oncogenic transformation and promotes tumour growth." (PMID 29311633, 2018). "The mechanism of wogonoside against tumor metastasis was mainly on account of the blocked TRAF2/4-Twist1 axis." (PMID 28774312, 2017).
tumor (continued). "Tumor cell proliferation, survival and migration are regulated by the deletion of ovarian carcinoma 2/disabled homolog 2 (DOC-2/DAB2) interacting protein (DAB2IP), a tumor suppressor that serves as a scaffold protein for H-Ras and TRAF2." (PMID 27036023, 2016). "CYLD, a tumor suppressor and a target gene of NF-κB, negatively regulates NF-κB and JNK activation by removing K63-linked polyubiquitin chains from TRAF2 and TRAF6 as well as several other signaling proteins." (PMID 23758787, 2013). "Taken together, these results support a model in which EI24 coordinates EMT and tumor progression through the regulation of TRAF2-mediated NF-κB activity." (PMID 24280371, 2013). "The results suggest that TRAF2 is important for T-lymphocyte-dominated immunomodulation in the LIHC tumor microenvironment and may influence LIHC development through it." (PMID 40144665, 2025). "The expression of TRAF2 was increased in the tumor group compared to normal (p < 0.0001)." (PMID 40560737, 2025). "Of note, in hereditary diffuse gastric cancer, the role of TRAF2 in promoting EMT could be particularly important since this tumor displays E-cadherin gene (CDH1) germline or somatic mutations, which correlate with increased aggressiveness and poor prognosis." (PMID 40229245, 2025). "Also, the silencing of copine 1 (CPNE1), a TRAF2 interactor, induced cell cycle arrest in PCa cells and this anti-tumor effect was reversed by overexpressing TRAF2." (PMID 40229245, 2025). "Since TRAF2 promotes the expansion and tumor infiltration of immune suppressive cells, favoring immune escape, it might also shape the TME immunological characteristics." (PMID 40229245, 2025). "It was revealed that the infiltrating abundance of tumor-infiltrating immune cells (TIIC) was significantly correlated with TRAF2 expression in a wide range of malignancies, and that TRAF2 expression was strongly associated with CD4T cells, CD8T cells, and B cells." (PMID 40144665, 2025). "In addition, we validated this finding using the LIHC scRNA-seq dataset obtained from the GEO dataset (GSE162616), and the results suggested the presence of high expression of TRAF2 in T-cells, NK-cells, and tumor cells." (PMID 40144665, 2025). "However, the role of TRAF2 expression in epigenetic, cancer prognosis, and immune responses in tumor microenvironment is unclear." (PMID 40144665, 2025). "In addition, although these findings point to new directions for follow-up studies, there is still a need to further investigate the potential biological function and molecular mechanisms of TRAF2 in tumor immunity using experiments." (PMID 40144665, 2025). "Subsequently, we examined whether Butein affects the expression levels of the downstream proteins TRAF1 and TRAF2 in the TWEAK/FN14 signaling pathway within tumor tissue." (PMID 41458609, 2025). "Our findings showed that reducing TRAF2 levels led to a significant decrease in colony formation and cellular proliferation, aligning with previous research that implicates TRAF2 in tumor progression." (PMID 40560737, 2025). "Importantly, the correlation between KHDC4 and TRAF2 among different pathologic tumor stages and lymph node metastasis was reflected in the Gleason score evaluation system based on PCa tissue biopsy." (PMID 40560737, 2025). "Similarly, as the concentration of Butein increased, the protein expression levels of TRAF1 and TRAF2 in tumor tissue declined correspondingly." (PMID 41458609, 2025). "In HCC, PLX-4720 bound to AXIN1 to block tumor proliferation in TRAF2−/− mice on a high-fat diet." (PMID 40901678, 2025). "We examined the effect of TRAF2 on the tumor immune microenvironment by assessing immune cell infiltration using four different analytical methods (MCPCOUNTER, QUANTISEQ, EPIC, and TIMER) using the ESTIMATE algorithm to analyze the ImmuneScore, the StromalScore, and the ESTIMATEScore." (PMID 40144665, 2025).
tumor (continued). "In addition, TRAF2 showed altered methylation levels in 28 tumor promoter regions and significant correlations with four methyltransferase genes." (PMID 40144665, 2025). "Further structural studies are needed to explore rare cases where TRAF2 may support anti-tumor immunity and to refine therapeutic approaches." (PMID 40229245, 2025). "TRAF2, which is a key player in cancer cell survival, has been described as a tumor promoter, but may also act as a tumor suppressor." (PMID 41515132, 2025). "Thus, TRAF2 is required for tumor formation in nude mice xenograft model with the mechanism associated with mTORC1 signaling pathway." (PMID 37081115, 2023). "Similarly, our results showed that TRAF2 knockdown resulted in decreased migration and invasion capability of tumor cells." (PMID 37415241, 2023). "Moreover, our findings undoubtedly deepen the understanding of how TRAF2 regulates tumor progression through the TME." (PMID 37415241, 2023). "Similarly, p62 knockdown significantly reversed tumor growth inhibition by TRAF2 knockdown with increased tumor volume and weight." (PMID 37081115, 2023). "In animal models of BCa, administration of pharmacological inhibitors of TRAF2/4 (Std.MD: − 3.36, 95% CI: − 4.53, − 2.18, P < 0.00001) or TRAF6 (Std.MD: − 4.15, 95% CI: − 6.06, − 2.24, P < 0.0001) in mice is associated with reduction in tumour burden." (PMID 36944688, 2023). "Indeed, TRAF2 deletion significantly inhibited nude mice tumor formation, with a reduced tumor volume and tumor weight in sgTRAF2 nude mice compared to sgCtrl mice." (PMID 37081115, 2023). "Moreover, tumor cell-expressed TRAF2 has been identified as a major factor-limiting cancer cell killing by cytotoxic T-cells after immune checkpoint blockade." (PMID 36011046, 2022). "However, TRAF2 can also be context-dependent as a tumor suppressor, presumably by virtue of its inhibitory effect on the alternative NFκB pathway." (PMID 36011046, 2022). "Moreover, RANK-c requires its TRAF2 binding sites to elicit its tumor attenuating NFκB-inhibitory activity pointing to TRAF2 sequestration as mode of action." (PMID 36011046, 2022). "IHC staining analysis suggested that TRADD, VDAC3, JMJD7-PLA2G4B, and TRAF2 expression levels were upregulated in COAD tumor tissues compared with those in normal gastric tissues at the protein level, which was consistent with the expression pattern of the genes." (PMID 36505813, 2022). "Similarly, the E3 ligase carboxyl terminus of Hsp70-interacting protein (CHIP), which triggers TRAF2 degradation, has tumor suppressive activity in breast and gastric cancer cells." (PMID 36011046, 2022). "In addition to inflammation, TRAF2 also plays a tumor suppressive or oncogenic role in different types of cancers." (PMID 33670113, 2021). "TRAF2 and TRAF3 genes of tumor necrosis factor receptor (TNF-R)-associated factor (TRAF) family are involved in diverse cell signaling, and function as both tumor suppressor gene and oncogene." (PMID 34257589, 2021). "Furthermore, MSI1 inhibits miR-671-5p suppression of TNF receptor-associated factor 2 (TRAF2) to induce CSC characteristics and tumor invasion and silence signal transducer and activator of transcription 3 (STAT3) to enhance radioresistance in GBM." (PMID 35052701, 2021). "Genetic loss of TNF and its death-signaling molecules (e.g., Tnfr1 and Casp8) led to uncontrolled tumor growth, whereas loss of molecules involved in ubiquitinating RIPK1 (e.g., Traf2 and Birc2/3) resulted in tumor rejection following immune checkpoint blockade." (PMID 34752416, 2021). "Hence, these data suggest an evolutionary model where loss of whole chromosome 9 is selected as a driver event early in tumor evolution (e.g., due to CDKN2A), but then later leads to collateral sensitivity to immunotherapy, possibly due to 9q34 (TRAF2) loss." (PMID 33508232, 2021). "The growth of xenograft tumor significantly reduced after TRAF2 was silenced." (PMID 32566659, 2020).
tumor (continued). "The loss of sensitivity of tumor cells to TNF could be mediated by TRAF2, given that inhibition of TRAF2 in tumor cells re-sensitizes them to TNF in vitro and improves the efficacy of ICB in mice bearing ICB-resistant tumors." (PMID 33344447, 2020). "Importantly, according to multivariate Cox regression analysis, TRAF2 expression together with tumor diameter was independent prognostic factors in GC patients." (PMID 31130821, 2019). "TRAF2 expression together with tumor diameter was independent prognostic factors in GC patients." (PMID 31130821, 2019). "Similar to TRAF2 and also consistent with the frequent deletions and inactivating mutations of TRAF3 identified in human B cell malignancies, a tumor suppressive role for TRAF3 in B lymphocytes has been demonstrated by in vivo evidence obtained from mouse models." (PMID 30294322, 2018). "Together, these data suggest that TRAF2 is a tumor suppressor in many human cancers." (PMID 30294322, 2018). "Interestingly however, increasing evidence indicates that TRAF2 also plays oncogenic roles in epithelial cancers and some other neoplasms." (PMID 30294322, 2018). "Thus, TRAF2 acts as a tumor suppressor in B lymphocytes primarily by inhibiting the NF-κB2 pathway through the well-established cIAP1/2-TRAF2-TRAF3-NIK axis." (PMID 30294322, 2018). "Moreover, a recent study suggested that degradation of TRAF2 by CHIP results in reduced tumor invasiveness by inactivating NF-κB activity." (PMID 24280371, 2013). "Moreover, in sensitized tumor states caused by TRAF2 and cIAP1/2 depletion, the loss of non-canonical IKK proteins in the TNFR1 complex emerged as the sole shared feature." (PMID 41315176, 2025). "Therefore, TRAF2/CD47 pathway regulated tumor innate immune response." (PMID 39665172, 2025). "Furthermore, TRAF2 depletion impaired the migratory and invasive capabilities of PCa cells, emphasizing its critical role in tumor malignancy." (PMID 40560737, 2025). "However, the expression pattern of TRAF2 in ccRCC and its impact on patient prognosis and tumor progression are unknown." (PMID 37415241, 2023). "Therefore, Fn14-dependent TRAF2-cIAP1/2 sequestration could also be a process that could be exploited for tumor therapy (see also below)." (PMID 36339601, 2022). "Furthermore, the miR-671-5p/TRAF2 group had a significantly higher tumor growth rate than the miR-671-5p group (p = 0.00943), suggesting that TRAF2 might overcome the biological effects of miR-671-5p." (PMID 35052701, 2021). "In addition, the expression of key genes in the TNF-α/NF-κB signaling, including NFKB1 (p50), RelA (p65), TNFRSF1A (TNFR1), TNFR1-associated death domain protein (TRADD), and TNF receptor-associated factor 2 (TRAF2), was examined in the cell lines and tumor tissues of EBV-associated cancers." (PMID 35008199, 2021). "In summary, we conclude from our data that targeting the TNFR1/TRAF2/IKK/NFκB signal transduction pathway might be a strategy for inhibiting inflammation-related cell fusion events within a tumour as it could give rise to cancer cell ×normal cell hybrids that could exhibit novel properties." (PMID 31266502, 2019). "Thus, TRAF3 and TRAF2 are tumor suppressive, whereas TRAF1 appears to be oncogenic in B cells." (PMID 23758787, 2013). "Experimental data further confirmed that Butein markedly downregulated the protein and mRNA expression levels of TWEAK, FN14, TRAF1, TRAF2, and TRAIL-R3 in cSCC tumor tissue." (PMID 41458609, 2025). "TRAF2 is recruited by IRE1, where it forms a complex that activates the NF-κB pathway and the subsequent transcription of anti-apoptotic genes, which help tumor cells resist ER stress-induced cell death." (PMID 40229245, 2025).
tumor (continued). "Here we found that TRAF2 induced CD47 ubiquitination, leading to inhibition of CD47 autophagic degradation, which in turn facilitated tumor immune escape." (PMID 39665172, 2025). "PCNA, BCL2, TRAF2, XIAP and FKBP5 expression levels in whole RNAs extracted by 36 tumor tissue samples were quantified as relative expression, using expression from healthy donor PBMCs as a reference sample (=1)." (PMID 41256864, 2025). "By integrating phenotypic assays with transcriptomic profiling, distinct downstream effectors were revealed—including TRAF2 and LOXL2—that connect TFAM dysregulation to cell cycle control, metabolic reprogramming, and tumor invasiveness." (PMID 41226485, 2025). "Evident by comparison to their cognate normal tissue analogs, discernible upregulation was registered across a slew of tumor tissues for PPIA, TRAF2, TRIM28, and HGS." (PMID 38460947, 2024). "First, our results showed that the expression of TRAF2 was positively correlated with CD206 (p = 0.029, R = 0.095) and CD301 (p = 2.4e-05, R = 0.18) in 539 TCGA-KIRC tumor samples." (PMID 37415241, 2023). "Since we learned that TRAF2 is a M2 MRG through bioinformatics analysis, we tried to study the possible role of TRAF2 in M2 macrophages promoting tumor progression." (PMID 37415241, 2023). "Quantitative polymerase chain reaction (qPCR) showed TRAF2 mRNA levels were increased both in HCC cell lines and HCC clinical tissues compared to normal liver HL7702 cells and adjacent non-tumor tissues, respectively." (PMID 37081115, 2023). "We found that MAP2K6, MAP3K5, MAP3K9, MAP3K12, RPS6KA2, RPS6KA5, and STAT1 were lowly expressed in tumor tissues; However, NFKB1, RAC1, SHC1, and TRAF2 are highly expressed compared to normal tissues." (PMID 36969076, 2023). "In our previous work, we have identified a differential reliance on TRAF2 and BIRC2 to establish resistance to TNF in different tumor cell lines." (PMID 37398651, 2023). "Significantly high expression of TRAF2, PGAM5 and ATG1621 in the tumour group was an unfavourable prognostic factor." (PMID 35293027, 2022). "Soon after TRAF2 and TRAF1 were described the first time, there was evidence that TRAF2 can also play a role in tumor biology." (PMID 36011046, 2022). "Most of these mutations are found in the gene of TRAF3 but mutations negatively affecting expression or function of TRAF2 were also frequently found defining TRAF2 (and TRAF3) in MM as a tumor suppressor." (PMID 36011046, 2022). "Against the background that TRAF2 and cIAPs protect tumor cells against the cytotoxic action of CD8+ T-cells and NK cells after ICB, combination therapies of TRAF2 inhibitors and checkpoint inhibitors appears particularly interesting." (PMID 36011046, 2022). "In view of the relevance of TRAF2 and the cIAPs to protect from TNFR1-induced cell death (see Section 3.1), this suggested that the sensitivity of tumor cells for TNF cytotoxicity is a crucial factor for ICB efficacy." (PMID 36011046, 2022). "In vivo, the GBM tumor size was inversely correlated with miR-671-5p expression, but tumorigenesis was promoted by STAT3 and TRAF2 activation in the miR-671-5p-positive GBM population." (PMID 35052701, 2021). "Notably, EI24 could suppress NF-κB activity by interacting with the complex I component TNFR-associated factors 2/5 (TRAF2/5) and causing their lysosome-dependent degradation, resulting in reduction of EMT- and inflammation-linked gene transcription and repression of tumor progression." (PMID 32974192, 2020). "After TRAF2 was knocked down, both the cell proliferation and colony formation of NPC cells are significantly suppressed, and the tumorigenesis and tumor growth rate in nude mice are substantially decreased." (PMID 32566659, 2020). "On the other hand, we found the expression of TNF-α, TRAF2 and TRAF4 was enhanced in the primary tumor as time goes on." (PMID 28774312, 2017).